TOP2A (DNA topoisomerase II alpha)
Diseases named in the same sentence as TOP2A in open-access papers (continued):
Sharing a sentence is not in itself a finding about the gene and the disease.
breast carcinoma (continued). "Of these candidate oncogenes, several, notably TOP2A, PNMT and UBE2C, have appeared in prognostic gene expression signatures, thus re-emphasizing their important role in breast cancer." (PMID 17925008, 2007). "Bioinformatic analysis yielded several differentially expressed cell-cycle-related genes, from which we selected Aurora kinase A (AURKA) and topoisomerase IIα (TOP2A) for RT-qPCR and western blot validation in MDA-MB-231 and MCF7 breast cancer cells, as well as normal breast epithelial cells (HMEC)." (PMID 37888205, 2023). "Additionally, CENPE, TOP2A, CENPF, TTK, and NDC80 are highly expressed in the cell cycle of basal-like breast cancer." (PMID 35496042, 2022). "Many studies have shown that TOP2A can be a prognostic biomarker and potential therapeutic target for bladder cancer, such as bladder urothelial carcinoma (BLCA), lung adenocarcinoma, prostate cancer, colon cancer and breast cancer." (PMID 35033076, 2022). "Thus, many studies have shown that the expression and/or co-expression of several genes, such as ERCC1, RRM1, TOP1, TOP2α, TUBB3, TYMS, and GSTP1, in tumor tissues is closely related to chemoresistance and prognosis in breast cancer patients (BC)." (PMID 35204496, 2022). "An avalanche of evidence has shown that TOP2A is overexpressed in various cancers, including HCC, malignant peripheral nerve sheath tumor, hepatoblastoma, breast cancer (BC), esophageal cancer, gastroesophageal cancer, pancreatic cancer, colorectal cancer (CRC), and prostate cancer (PCa)." (PMID 34939898, 2021). "Among the breast cancer patients with TOP2A overexpression, the absence of clinical response to anthracycline-containing neoadjuvant chemotherapy is associated with the presence of M2+ macrophage phenotype." (PMID 33150086, 2020). "It has been reported that LINC00461/miRNA-149-5p/LRIG2 existed in hepatocellular carcinoma, LINC00461/miRNA-15a/miRNA-16/Bcl-2 happened in multiple myeloma, LINC00461/miRNA-30a-5p/integrin β3 occurred in breast cancer, and LINC00461/miRNA-411-5p/TOP2A participated in glioma." (PMID 33817241, 2020). "In other studies, TOP2A was upregulated in cancer tissues when compared with that of adjacent non-cancerous tissues in breast cancer, renal cell carcinoma, ovarian cancer, prostate cancer, nasopharyngeal carcinoma, and colon cancer." (PMID 31105744, 2019). "For example, we showed previously that relative expression of proliferation-related and immune response-related genes, i.e., UBE2C, TOP2A, RRM2, FOXM1, MK167, and BTN3A2, provided a prediction value of adjuvant chemotherapy benefit for patients with ER+/HER2− early breast cancer." (PMID 31779659, 2019). "In the present study, we found that AME can cause S-phase arrest of breast cancer cells, downregulate the expression of CDC20, AURKB, PLK1, CCNB2, and TOP2A, and upregulate the expression of GADD45A, eventually inhibiting the proliferation of breast cancer cells." (PMID 31275405, 2019). "In conclusion, the clinical significance of TOP2α in breast cancer has not yet been clarified, being a mandatory research area in this field." (PMID 31301170, 2019). "Although TOP2A status has several important implications in breast cancer, the standard tools and cutoff values for estimating TOP2A status have not been established." (PMID 29928479, 2018). "We retrospectively evaluated the prognostic value of TOP2A status in these patients with non-metastatic breast cancer." (PMID 29928479, 2018). "First, TOP2A amplified did not affect the prognosis of HER2 positive breast cancer treated with standard adjuvant treatment of trastuzumab-containing chemotherapy." (PMID 29928479, 2018). "In addition, BG+/-TMZ significantly decreased p-CDC2, p-AURKB, p-TOP2A, p-KIF20A and p-CDC20 expression in breast cancer cells." (PMID 30038716, 2018).
breast carcinoma (continued). "In contrast, the TOP2A amplified is limited in HER2 positive breast cancer, and the presence of the TOP2A amplified does not influence the survival advantage of adjuvant anthracycline therapy." (PMID 29928479, 2018). "The prognostic value and the best method of testing of topoisomerase II alpha (TOP2A) status have not been established in modern tailored therapy based on breast cancer subtype." (PMID 29928479, 2018). "Second, previous reports showing the predictive value of TOP2A amplified compared anthracycline-based chemotherapy regimens with CMF, which is no longer used as a standard treatment regimen for HER2 positive breast cancer." (PMID 29928479, 2018). "In BCIRG-006, HER2 positive breast cancer was treated with anthracycline, taxane, plus trastuzumab showed equivalent prognoses, irrespective of TOP2A status (5-year DFS; TOP2A amplified vs. normal/deleted, 85% vs. 83%)." (PMID 29928479, 2018). "The topoisomerase II alpha (TOP2A) and ERBB2 genes are located close to each other on the long arm of chromosome 17 and may be co-amplified in breast cancer." (PMID 27576528, 2016). "TOP2A gene amplifications predict improved efficacy of epirubicin in patients with breast cancer and thus could be an alternative option for patients with CRC and amplified TOP2A gene." (PMID 26867764, 2016). "TOP2A amplification predicts improved efficacy to epirubicin in patients with breast cancer and thus could be an alternative option to irinotecan-based therapy in patients with CRC and TOP2A amplification who relapsed on oxaliplatin containing chemotherapy." (PMID 26867764, 2016). "Three important proliferation genes for breast cancer are RACGAP1, TOP2A and Ki67." (PMID 27695115, 2016). "Previously, some studies in prostate cancer, breast cancer, and gastric carcinomas also reported that TOP2A overexpression is not closely correlated with TOP2A amplification, in contrast to the strong correlation of HER2 overexpression with HER2 amplification." (PMID 25695068, 2015). "TOP2A gene amplification and TOP2A deletion could be found in 35% and 5% of HER2-amplified breast cancer, respectively; however, only TOP2A gene deletion could be detected in 3% of HER2 nonamplified breast cancer." (PMID 25695068, 2015). "Quite the contrary, breast cancer survival can be predicted by TOP2B rather than TOP2A expression level." (PMID 25406834, 2014). "There is a very recent report from the Breast Cancer International Research Group (BCIRG) 006 trial and an additional retrospective analysis of almost 5,000 patients regarding the efficacy of trastuzumab in breast cancer patients with HER2 and TOP2A co-amplification." (PMID 23092535, 2012). "Conversely, the subgroup of patients with ER/PR-negative breast cancers and nonamplified (normal or deleted) TOP2A showed the least favorable RFS and OS rates in our population." (PMID 21288332, 2011). "In addition, the topoisomerase II α gene, TOP2 α, is located at chromosome band 17q12-q21, close to the ErbB-2 oncogene (HER-2/neu), which is the most commonly amplified oncogene in breast cancer." (PMID 17551498, 2007). "In 97 breast cancers, these authors found no Topo IIα gene copy aberrations when the Her-2/neu gene status was normal, yet when Her-2/neu was amplified, TOP2α was coamplifed in 44% and deleted in 42% of the cases." (PMID 12915875, 2003). "Unlike CCNB1, CCNA2, and CDK1, currently, the remaining genes (TOP2A, KIF11, and MELK) are not found to be associated with cell cycle; their dysfunctions might still affect the progression and prognosis of breast cancer." (PMID 31428132, 2019). "Our data from cell cycle analysis and real-time PCR suggested that AS extract exerted mild stimulatory activities in breast cancer cells at S phase; however, it did not up-regulate the tested proliferation-related genes, TOP2A and RacGAP1, as well as survival-related gene, survivin." (PMID 31293425, 2019).
breast carcinoma (continued). "Moreover, six hub genes were selected and validated in clinical sample for further analysis owing to the high degree of connectivity, including CDK1, CCNA2, TOP2A, CCNB1, KIF11, and MELK, and they were all correlated to worse overall survival (OS) in breast cancer." (PMID 31428132, 2019). "Knowing that ERBB2 and TOP2α genes are located in the same chromosome in human and cat genomes, we analyzed the DNA copy number of ERBB2 and TOP2α genes in a collection of feline mammary tumors (n=27), always in comparison with the disease-free tissue from the same individual." (PMID 31301170, 2019). "At our institution, both TOP2A overexpression and TOP2A amplified had been consecutively evaluated using immunohistochemistry (IHC) and fluorescence in situ hybridization (FISH) in patients with breast cancer between May 2005 and April 2015." (PMID 29928479, 2018). "Molecular biomarker HER2, but not CCND1 and TOP2A, may be a critical factor as a predictor of breast cancer prognosis." (PMID 25202398, 2014). "This could be true specifically for breast cancer given the expression of TOP2B in >90% of breast cancer while TOP2A expression is limited in breast tumors as well as since TOP2B rather than TOP2A has been shown to be a better predictor for breast cancer survival in patients." (PMID 37927589, 2023). "In a single arm study of adjuvant docetaxel and cyclophosphamide plus trastuzumab in patients with HER2-amplified breast cancer, patients with or without TOP2A amplified had excellent prognoses (3-year DFS; TOP2A amplified vs. normal/deleted, 97.2% vs. 96.4%)." (PMID 29928479, 2018). "We demonstrate that CA IX expression is correlated with worse PFS and OS for breast cancer patients treated with doxorubicin, independent of HER2 or TOP2A gene amplification." (PMID 22333602, 2012). "The TOP2A gene is located adjacent to the HER-2 oncogene at the chromosome location 17q12q21 and is either amplified or deleted in breast cancer, with or without HER-2 amplification." (PMID 21785684, 2011). "We also demonstrated an increasing expression of TOP2A protein on an independent test set of HNB/benign/reductionmammoplasties, atypical-ductal-hyperplasia with and without synchronous breast cancer, DCIS and IDC tissues using a custom tissue microarray (TMA)." (PMID 21785684, 2011). "Indeed, besides TOP2A, other genes which are located not only in the HER2 smallest region of amplification (SRA) but also all along the long arm of the Chr17 might also be amplified, and they could play functional roles in breast cancer development and progression." (PMID 21288332, 2011). "TOP2A gene is coamplified with HER2 gene in approximately 35% of HER2-amplified breast cancers, and TOP2A coamplification, not HER2 amplification, is the predictive marker of an incremental response to anthracycline-based chemotherapy in HER2-amplified breast cancers." (PMID 25695068, 2015). "TOP2A overexpression is a strong indicator of poor prognosis in prostate cancer and in nasopharyngeal carcinoma as well as in the subgroup of HER2 negative breast cancer." (PMID 25695068, 2015).
prostate carcinoma (61 papers, 2011 to 2025). A carcinoma that arises from epithelial cells of the prostate gland. "In terms of radiotherapy, TOP2A has been implicated in the development of radio-resistance in prostate cancer." (PMID 40290723, 2025). "In a previous report, the accumulation of TOP2A induced by SPOP mutations was found to facilitate prostate cancer progression through the accumulation of DNA damage, and etoposide was found effective against SPOP-mutated prostate cancer." (PMID 38732035, 2024). "In a study, it was shown that prostate cancer with a high TOP2A expression was associated with a lower survival rate." (PMID 37895364, 2023). "Upregulated expression of TOP2A is associated with recurrence after radiotherapy in prostate cancer patients." (PMID 38012642, 2023). "Researchers have discovered that lncRNA SNHG3 is associated with miR-577/SMURF1 in prostate cancer and miR-139-5p/TOP2A in renal cell carcinoma." (PMID 36497046, 2022). "Our analysis of a prostate cancer cohort suggested that TOP2A expression was associated with tumor progression and chemoresistance." (PMID 34782700, 2021). "Overexpression of TOP2A is associated with risk of systemic progression in prostate cancer patients, and higher levels of TOP2A were found in hormone-resistant cases." (PMID 26560244, 2015). "Increased expression of proliferation associated proteins Ki67 and TOP2A has been found to be more highly prognostic in ERG-negative prostate cancers." (PMID 26172920, 2015). "More recently, TOP2A transcript and protein levels havebeen associated with systemic progression of prostate cancer." (PMID 21629784, 2011). "TOP2A has been associated with many solid cancers such as breast and prostate cancers." (PMID 32024004, 2020). "Furthermore, TOP2A expression has been previously linked to EZH2 expression in aggressive prostate cancer." (PMID 29200404, 2018). "Surprisingly, although TOP2Ahigh (high expression of TOP2A) cells were highly proliferative and were associated with recurrence/metastasis in prostate cancer, CSCs were enriched in a small minority which was TOP2Aneg (undetectable expression of TOP2A by FACS in promoter reporter system)." (PMID 25237769, 2014). "For example, as a key oncogene in the prostate, TOP2A is highly expressed in patients with metastatic prostate, which can be used as a biomarker for early diagnosis and treatment of prostate cancer." (PMID 37980167, 2023). "The BAZ2A-TAM domain, in association with RNA, promotes the interaction with TOP2A and KDM1A that serves to repress genes critical to prostate cancer progression." (PMID 37184661, 2023). "Previous studies have identified dual upregulation of EZH2 and TOP2A as biomarkers for early identification of increased metastatic potential and recurrence among patients undergoing radiotherapy for prostate cancer." (PMID 38008711, 2023). "The time-dependent ROC curve demonstrated that CENPF and TOP2A show good predictive value in prostate cancer patients." (PMID 36937411, 2023). "The survival analysis revealed that progress-free interval is closely associated with the expression level of CENPF, TOP2A, and OR51E2 in the prostate cancer cohort." (PMID 36937411, 2023). "TOP2A can be used as an indicator for early detection and diagnosis of aggressive prostate cancer subsets." (PMID 36531013, 2022). "To investigate the clinical significance of TOP2A expression, we evaluated the correlation between TOP2A expression and prostate cancer prognosis using The Cancer Genome Atlas (TCGA) prostate cancer cohort dataset." (PMID 34782700, 2021). "The results showed that 7 genes were all associated with prostate cancer prognosis, but only UBE2C, TOP2A and CCNB1 were high expression in prostate cancer samples than normal prostate gland samples, the expression of PBK, CDKN3, AURKA, MKI67 were not." (PMID 33630978, 2021). "Higher TOP2A expression was a poor prognostic factor in The Cancer Genome Atlas prostate cancer cohort." (PMID 34782700, 2021).
prostate carcinoma (continued). "Other targets that have been associated with prostate cancer metastasis (or progression) include BIRC5/survivin, EZH2, TOP2A, HMMR, LPL, and SSTR1." (PMID 34680307, 2021). "TOP2A upregulation is closely associated with various tumor types, including breast, ovarian, and prostate cancers, because TOP2A catalyzes the cleavage of double-stranded DNA and promotes transcription during mitosis." (PMID 34094915, 2021). "In the Fred Hutchinson (FH) cohort, which included patients with metastatic disease, TOP2A expression was significantly upregulated in metastatic prostate cancer tissues." (PMID 34782700, 2021). "In serum, CNV in CCND1 was associated with MVI (p = 0.004); CNV in PTP4A, KRAS, ERBB2, TOP2A with positive STSM (p ≤ 0.035); CNV in CCND1 with the presence of incidental prostate cancer (p = 0.018)." (PMID 33298978, 2020). "To determine our prediction, we found CCNB1, CKS2, MKI67, RRM2, TK1 and TOP2A acted as independent prognostic factors in TCGA prostate cancer." (PMID 32266115, 2020). "Previous studies confirmed that the aberrant TOP2A expression was observed in various cancer subtypes, such as breast, colon, ovarian, gastric, prostate cancer, and HCC." (PMID 33376723, 2020). "Tissue sections from LNCaP prostate cancer cell xenografts in mice were chosen to visualize the spatial variation of TOP2A mRNA using our technique." (PMID 29335461, 2018). "Recently, TOP2A, MELK, and CENPF were also reported to be putative targets of miR-27a-5p and have been implicated in prostate cancer progression." (PMID 29415999, 2018). "We demonstrate this method by amplifying TOP2A messenger RNA (mRNA) in a prostate cancer xenograft with 100 μm spatial resolution and by visualizing the variation in threshold time of amplification across the tissue." (PMID 29335461, 2018). "To elucidate the mechanism by which high levels of TOP2A contribute to tumor progression we generated TOP2A overexpressing prostate cancer cell lines." (PMID 26560244, 2015). "To add clinical significance to our initial findings, we investigated the mRNA expression of Top2a in a recently published dataset of human prostate cancer from Memorial Sloan Kettering Cancer Center (MSKCC, GEO: GSE211032)." (PMID 25605014, 2015). "To determine the impact of TOP2A expression on prostate cancer, we analyzed 4 larger cohorts of prostate cancer specimens with clinical annotations." (PMID 25237769, 2014). "More importantly, we found that high expression of TOP2A correlates with advanced disease stages, tumor recurrence/metastasis and poor patient survival in human prostate cancer." (PMID 25237769, 2014). "TOP2A was rarely detected in low-grade and post-castration prostate carcinomas but was expressed at high levels in high-grade or metastatic tumors." (PMID 25237769, 2014). "TOP2A gene expression was correlated with advanced stages of the disease, higher Gleason scores, aneuploidy formation and poor survival in prostate cancer." (PMID 25237769, 2014). "In this study, through systematic bioinformatic analyses, we have identified TOP2A as the most significantly upregulated gene in secondary prostate cancer." (PMID 25237769, 2014). "In this study, we systematically analyzed genes upregulated in secondary prostate cancer and identified TOP2A to be at the very top of the list." (PMID 25237769, 2014). "Our results indicated that TOP2A was the most highly upregulated gene in recurrent/metastatic prostate cancer, and its high expression was positively correlated with poor prognosis in patients." (PMID 25237769, 2014). "Several of the transcripts identified in the CTCs have been correlated with aggressive behavior in localized prostate cancer (e.g. PLK-1, TOP2A) so it is interesting to observe these markers in cells from patients with highly advanced prostate cancers." (PMID 23145101, 2012). "However, the relationship between TOP2A and androgen independence or chemoresistance in prostate cancer is unclear." (PMID 34782700, 2021).